MIR4509-1 (microRNA 4509-1)
Synonyms: hsa-mir-4509-1
Gene: MicroRNA gene on chromosome 15 (23,197,827 to 23,197,920, forward strand). Ensembl gene ENSG00000276941.
Homologues: Paralogues in human: MIR4509-2 (100% identical), MIR4509-3 (100% identical).